ABCB1 (ATP binding cassette subfamily B member 1)
Diseases named in the same sentence as ABCB1 in open-access papers (continued):
Sharing a sentence is not in itself a finding about the gene and the disease.
Parkinson disease (6 papers, 2012 to 2020). A progressive degenerative disorder of the central nervous system characterized by loss of dopamine producing neurons in the substantia nigra and the presence of Lewy bodies in the substantia nigra and locus coeruleus. "We collected 12 studies with a total of 2365 cases and 2977 controls to estimate the association between ABCB1 3435C/T polymorphism and the risk of Parkinson's disease in our meta-analysis." (PMID 27749554, 2016). "Polymorphisms in the Abcb1 gene have been recognized in Parkinson's disease patients, and PET studies have shown decreased function of PGP in Parkinson's disease." (PMID 23986663, 2013). "In addition, ABCB1 1236C/T polymorphism might be connected to Parkinson's disease but their relationship showed a little more complex." (PMID 27749554, 2016). "Recently, the polymorphisms of several genes, such as CYP1A1, CYP1A2, ABCB1, PON1, PON2, and NOS1, were considered as the candidate risk factors for Parkinson's disease." (PMID 27749554, 2016). "Alternatively, it is also possible that certain genetic variations in ABCB1 have a more primary role in developing neurodegenerative diseases such as AD or Parkinson's disease (PD)." (PMID 23067778, 2012). "Therefore, this study denoted that ABCB1 3435C/T polymorphism might not play a role in Parkinson's disease." (PMID 27749554, 2016).
renal carcinoma (6 papers, 2014 to 2024). A carcinoma arising from the epithelium of the renal parenchyma or the renal pelvis. "Furthermore, induced Wnt/β-catenin signals by several proteins lead to increased ABCB1 expression level and promote drug resistance in different cancer cells such as the PITX2 protein in renal cancer cell lines and retinoic acid receptor gamma in cholangiocarcinoma." (PMID 25401518, 2014).
status epilepticus (6 papers, 2011 to 2026). Status epilepticus is defined as a continuous seizure lasting more than 30 min, or two or more seizures without full recovery of consciousness between any of them. "Downregulation of miR146a-5p increased Abcb1 protein levels at the blood-brain barrier of rats with status epilepticus." (PMID 36973040, 2023). "Additionally, injecting miR-146a-5p into the hippocampus of rats with status epilepticus decreased Abcb1 mRNA and protein expression." (PMID 36973040, 2023).
T-cell lymphoma (6 papers, 2005 to 2025). "Compounds 1–3 were evaluated for their effects on the reversion of multidrug resistance (MDR) mediated by P-glycoprotein through use of the rhodamine-123 exclusion screening test on human ABCB1 gene transfected L5178Y mouse T-cell lymphoma." (PMID 26732580, 2015). "In doxorubicin-resistant human T-cell lymphoma cells (CEM/ADR5000), ATRA outperformed verapamil in suppressing ABCB1 activity at non-cytotoxic concentrations of 20, 50, and 100 μM in the Rh-123 assay, and at 10, 20, 50, and 100 μM in the calcein-AM assay." (PMID 41303640, 2025).
uterine sarcoma (6 papers, 2014 to 2025). "Their activity was tested in vitro using a MDR model systemconsisting of a cocultured MES–SA uterine sarcoma cell lineand its P-gp (ABCB1) overexpressing variants." (PMID 40644622, 2025). "ABCB1 in the multidrug-resistant uterine sarcoma lineconferred significant resistance against lepidiline A and the copper-lepidilineA complex, but not against the silver and gold complexes." (PMID 39072085, 2024). "We previously reported activation of the Wnt pathway in ABCB1-overexpressed human uterus sarcoma drug-resistant MES-SA/Dx5 cells through active β-catenin and associated transactivation activities, and upregulation of Wnt-targeting genes." (PMID 25401518, 2014). "The cytotoxicity of all compounds was tested in an in vitro triple coculture model system for ABCB1-mediated MDR in uterine sarcoma lines, and a subset was probed against a triple-negative, BRCA1-deficient murine breast cancer line and its cisplatin-resistant derivative." (PMID 41373545, 2025).
acute coronary syndrome (5 papers, 2011 to 2022). Signs and symptoms related to acute ischemia of the myocardium secondary to coronary artery disease. "Ticagrelor was found to be more efficacious for acute coronary syndrome than clopidogrel, irrespective of CYP2C19 and ABCB1 polymorphisms." (PMID 23908855, 2013). "The TRITON TIMI 38 study on patients with acute coronary syndrome treated with PCI following clopidogrel versus another thienopyridine, “prasugrel,” explored the role of ABCB1, a glycoprotein that might affect clopidogrel transport and metabolism." (PMID 22135769, 2011).
acute promyelocytic leukemia (5 papers, 2005 to 2025). An aggressive form of acute myeloid leukemia (AML), characterized by arrest of leukocyte differentiation at the promyelocyte stage, due to a specific chromosomal translocation t(15;17) in myeloid cells. "In the promyelocytic leukemia HL-60, the promoters of ABCB1 and ABCG2 were highly methylated." (PMID 27689338, 2016). "Interestingly, FK228, a class I HDAC inhibitor, induced ABCB1 overexpression in normal peripheral blood mononuclear cells, in circulating tumor cells, acute promyelocytic leukemia cells and osteosarcoma." (PMID 25268163, 2014). "In the promyelocytic leukemia cell line HL-60, lacking ABCB1 expression, two CpGs (CpG 17 and 37) in the ABCB1 gene, one upstream and one downstream of the transcription start site, were fully methylated." (PMID 33066132, 2020). "Moreover, in acute promyelocytic leukemia cells the co-administration of all-trans retinoic acid with FK228 increased acetyl-H3-Lys9 and acetyl-H4 at the ABCB1 promoter region." (PMID 25268163, 2014). "Furthermore, in acute promyelocytic leukemia NB4 cells lacking ABCB1 expression, ATRA increased ABCB1 mRNA levels, protein expression, as well as transporter activity, particularly when combined with the histone deacetylase inhibitor depsipeptide (FK228)." (PMID 41303640, 2025).
AIDS (5 papers, 2011 to 2025). A syndrome resulting from the acquired deficiency of cellular immunity caused by the human immunodeficiency virus (HIV). "ABCB1 1236CT, 1236TT, and 3435CT genotypes were associated with AIDS progression (p = 0.024, p = 0.026, and p = 0.005, respectively)." (PMID 41140414, 2025). "The ABCB1 3435T variant has been linked with good immune recovery in HIV/AIDS individuals, while the presence of the ABCB1 2677T variant has been strongly associated with virological failure." (PMID 23133441, 2012). "Therefore, the aim of this study was to investigate the role of genetic polymorphisms in ABCB1 on plasma efavirenz levels in HIV/AIDS patients in the South African population." (PMID 23133441, 2012). "The current study showed that the drug transporter ABCB1 contributes in predicting response to efavirenz treatment in the South African HIV/AIDS population." (PMID 23133441, 2012). "ABCB1 was also significant when assessed in the presence of age, sex, and whether the patient manifested AIDS in both the discovery and validation set of cases." (PMID 23372834, 2013). "Genotyping of AIDS patients for ABCB1 variation may help predict outcome and potentially could help guide treatment strategies." (PMID 23372834, 2013). "The aim of the study was to evaluate the role of polymorphisms in ABCB1 gene on plasma efavirenz levels and treatment response in the form of change in viral load and CD-4 cell count in HIV/AIDS patients receiving efavirenz-containing highly active antiretroviral treatment regimens." (PMID 23133441, 2012).
Anxiety (5 papers, 2012 to 2023). Intense feelings of nervousness, tension, or panic often arise in response to interpersonal stresses. "The present findings raise the question of whether ABCB1 and ABCG2 polymorphisms might explain genetic susceptibility to cannabis-induced psychosis or the adverse psychoactive effects of this drug (e.g. addiction, anxiety and cognitive impairment) by altering the brain disposition of THC." (PMID 22536451, 2012). "Finally, because anxiety is known to affect the perception of pain and Hamilton rating scale values were positively correlated with postoperative analgetic consumption, we have examined the effect of the ABCB1 C3435T genotype on Hamilton ratings, with negative results." (PMID 36749481, 2023).
autoimmune disease (5 papers, 2014 to 2024). A disorder resulting from loss of function or tissue destruction of an organ or multiple organs, arising from humoral or cellular immune responses of the individual to their own tissue constituents. "Determination of ABCB1 polymorphisms may be helpful when treating autoimmune diseases, including pemphigoid." (PMID 29948283, 2018). "P-glycoprotein encoded by ABCB1 gene is an ATP-dependent drug efflux pump, which has been detected in some autoimmune disease, such as SLE." (PMID 35860258, 2022).
cannabis dependence (5 papers, 2010 to 2025). Physical and psychological dependence on the drug cannabis. "Subsequently, this same group found a significantly higher frequency of the C allele and CC genotype of the ABCB1 rs1045642 SNP in patients with cannabis dependence compared to a control group." (PMID 36138925, 2022). "A recent study suggests P-gp regulates the brain disposition of THC, as an ABCB1 polymorphism was associated with an increased risk of developing cannabis dependence." (PMID 22536451, 2012). "This study showed that the ABCB1 variant C3435T (CC genotype) increased the risk of developing cannabis dependence, as this SNP was more prevalent in individuals dependent on cannabis than controls." (PMID 22536451, 2012). "Finally, cannabis dependence has been associated with the C3435T single nucleotide polymorphism (SNP) of the gene ABCB1, encoding for the membrane transporter P-glycoprotein." (PMID 27713377, 2010). "ABCB1 polymorphisms were studied for their role in cannabis addiction: the ABCB1 3435 SNP was related to cannabis dependence." (PMID 40407530, 2025). "Next, in a sample of patients with cannabis dependence who reported “heavy” use of cannabis (≥7 joints per week), they found a significantly higher mean plasma THC concentration in the ABCB1 rs1045642 CC genotype group compared to T-allele carriers (TT + TC)." (PMID 36138925, 2022). "The results from a series of gene-based tests indicated that ABCB1 variation was associated with alcohol dependence criteria (P=7.1 × 10-5) and cocaine dependence criteria (P=0.01), but not cannabis dependence criteria (P=0.19) or opioid dependence criteria (P=0.50)." (PMID 25918995, 2015).
Cerebral ischemia (5 papers, 2012 to 2025). Restriction of arterial blood supply to the brain associated with insufficient oxygenation to support the metabolic requirements of the tissue. "In Abcb1–/– mice not exposed to focal cerebral ischemia, increased microglial activation associated with hyporamification of this microglia has previously been demonstrated in the hippocampal CA3 region." (PMID 31572128, 2019). "The authors speculated that regulation of ABCB1 and ABCC1 as seen in cerebral ischemia could depend on other factors than hypoxia, such as glucose deprivation or reoxygenation." (PMID 22553972, 2012). "However, ABCB1 proved to be upregulated on focal cerebral ischemia in mice, but not in rats, whereas ABCC8 showed de novo expression on ischemia in rats." (PMID 22553972, 2012).
chondrosarcoma (5 papers, 2009 to 2023). A malignant cartilaginous matrix-producing mesenchymal neoplasm arising from the bone and soft tissue. "In this study, we identified higher levels of AR and ABCB1 expression in cisplatin-resistant human chondrosarcoma SW1353 cells (cis-SW) compared with cisplatin-sensitive SW1353 cells." (PMID 32428872, 2020). "In this study, we identified high levels of AR and ABCB1 expression in human chondrosarcoma cisplatin-resistant cells." (PMID 32428872, 2020). "Thus, ABCB1 plays an important role in AR-induced cisplatin resistance in human chondrosarcoma cells." (PMID 32428872, 2020). "We therefore speculated that ABCB1 expression correlates with levels of cisplatin resistance in chondrosarcoma cells." (PMID 32428872, 2020). "Few studies have investigated the role of ABCB1 in chondrosarcoma." (PMID 32428872, 2020). "Thus, our findings highlight the important role of ABCB1 in cisplatin resistance in chondrosarcoma." (PMID 32428872, 2020). "AR upregulates ABCB1 expression through the PI3K/Akt/NF-κB signaling pathway, and knockdown of AR sensitized chondrosarcoma cells to cisplatin in cellular and preclinical experiments." (PMID 32428872, 2020).
diffuse large B-cell lymphoma (5 papers, 2011 to 2023). "Additionally, one recent research confirmed the inhibitory effect of melatonin on ABCB1 expression in epirubicin-treated diffuse large B cell lymphoma cells." (PMID 36651944, 2023). "Germinal center B-cell-like (GCB) subtype of diffuse large B-cell lymphoma (DLBCL) was characterized by more gains at 7q22.1, which contained ABC transporter ABCB1 compared to activated B-cell-like (ABC) lymphoma, according to microarray analysis." (PMID 26799285, 2016).
Hand-foot syndrome (5 papers, 2015 to 2025). "The presence of a mutation on the ABCB1 gene can lead to diarrhea in some patients but minimize the reports of hand-and-foot syndrome." (PMID 36005935, 2022). "Hand-foot syndrome is prevalent in carriers of a copy of TTT in the ABCB1 (3435C/T, 1236C/T, 2677G/T) haplotype." (PMID 34948113, 2021). "While the ABCB1 haplotype of the present case was possibly TTT type, hand-foot syndrome did not appear." (PMID 26001650, 2015).
liver disease (5 papers, 2013 to 2023). "The ABCB1 is overexpressed in liver diseases such as cholestatic, biliary cirrhosis, and obstructive jaundice." (PMID 37993474, 2023).
metastatic colorectal cancer (5 papers, 2020 to 2024). "In a retrospective cohort of 63 patients diagnosed with metastatic colorectal cancer, a multivariate analysis revealed that liver metastases, DPYD, ABCB1, and MTHFR polymorphisms are independent indicators of poor prognosis, irrespective of oncogene mutations." (PMID 38248103, 2024). "A total of 132 metastatic colorectal cancer patients were genotyped for CYP3A4*1B, CYP3A4*18, CYP3A5*3, DPYD*2A, DPYD*5, DPYD c.1774C > T, UGT1A1*28, UGT1A1*6, ABCB1 c.1236C > T, ABCB1 c.3435C > T, ABCC2 c.3972C > T, and ABCG2 c.421C > A." (PMID 32778670, 2020).
metastatic tumors (5 papers, 2019 to 2024). "In another dataset of patients with metastatic disease, an association was observed between higher Gleason scores and increased ABCB1 mRNA expression." (PMID 38346967, 2024). "It has been observed that the proportion of tumor cells expressing ABCB1 increased in some metastatic tumors from patients that have undergone multiple cycles of chemotherapy." (PMID 31830995, 2019). "Furthermore, the analysis of advanced and metastatic tumors revealed a significant relationship between higher ABCB1 mRNA levels and an increased incidence of metastasis compared to patients with local recurrence." (PMID 38346967, 2024). "More investigations must be undertaken in order to evaluate the real benefits that the gained from the upregulation of ABCB1 and ABCC1 on invasiveness and aggressiveness of metastatic tumors." (PMID 37047018, 2023).
Myalgia (5 papers, 2015 to 2023). "The results of our study indicate that myalgia, the most common side effect in atorvastatin users, is associated with polymorphisms in the ABCB1 gene." (PMID 37857778, 2023). "Single nucleotide polymorphisms of the ABCB1 and SLCO1B1 genes have been associated with decreased and increased incidence of myalgia and myositis respectively." (PMID 28771594, 2017). "One study evaluated the effect of the ABCB1 haplotypes (1236C>T, 2677G>A/T and 3435C>T) on TC and LDL-C responses to simvastatin and demonstrated a reduction in the T–non-G–T haplotype frequency in patients with myalgia compared with the non-ADR group (P = 03)." (PMID 26438079, 2015).
myeloid leukemia (5 papers, 2020 to 2024). A clonal proliferation of myeloid cells and their precursors in the bone marrow, peripheral blood, and spleen. "All together these data demonstrate that the acquisition of an ABCB1-dependent daunorubicin-resistant cellular state in myeloid leukemia cells is associated with sustained upregulation of an ISR-like transcriptional program, with the transcription factor ATF4 at its core." (PMID 31770110, 2020). "Acquired drug resistance through the elevated regulation of ABCB1 after chemotherapy is evidenced in myelogenous leukemia, a hematological malignancy." (PMID 34208283, 2021). "ABCB1 promoter translocations have been described in several solid malignancy cancer cell lines but not in human myeloid leukemia cell lines." (PMID 33167906, 2020).
oral cancer (5 papers, 2016 to 2025). "In oral cancer, overexpression and genetic mutations of ABCB1 have also been reported and are thought to be among the causes of reduced efficacy of chemotherapeutic agents." (PMID 40362545, 2025). "ABCC1, also known as MRP1, has been involved in drug elimination in various tissues of the body, including oral cancer, like ABCB1." (PMID 40362545, 2025). "Besides, melatonin was discovered to decrease the expression of ABCB1 in melatonin-treated vincristine-resistant oral cancer cell lines via up-regulation of microRNA-34b which targets the ABCB1 gene." (PMID 36651944, 2023). "Additionally, pimozide was found to inhibit ABCB1 in drug-resistant KBV20C oral cancer cells, but the authors did not explain the mechanism." (PMID 34336684, 2021). "Hence, the scope of the present study is limited to uncover the molecular basis and a novel combination of GLU and PTX to simultaneously modulate pump and non-pump resistance for the treatment of ABCB1 over expressing in oral carcinoma KB cells in vitro." (PMID 27304668, 2016).
retinoblastoma (5 papers, 2016 to 2025). A malignant tumor that originates in the nuclear layer of the retina. "ABCB1 has been associated with chemoresistance in retinoblastoma." (PMID 36230889, 2022). "Thus, our findings suggest that the association of ABCB1 expression with chemoresistance in retinoblastoma is due to transcriptional reprogramming associated with PI3K/AKT signaling in many tumor cells, rather than outgrowth of chemoresistant stem cells." (PMID 36230889, 2022). "Cyclosporin has been used as a means of overcoming chemoresistance in retinoblastoma owing to its purported ability to inhibit ABCB1, although this mechanism of action has been questioned." (PMID 36230889, 2022). "Subsequent studies identified XIAP and ABCB1 as targets of miR-214-3p, and it was suggested that 214-3p sensitizes retinoblastoma cells to chemodrugs and promotes apoptosis by targeting XIAP (X-linked inhibitor of apoptosis) and ABCB1, which codes for the multi-drug resistance P-glycoprotein." (PMID 38256203, 2024). "However, an even more pronounced effect was observed by inhibiting ABCB1, the most highly upregulated of these genes, in carboplatin-resistant retinoblastoma cells." (PMID 36230889, 2022). "Specifically, enucleated eyes from chemotherapy-naive retinoblastoma patients showed high ABCB1 expression and thus, the resistance mechanisms that involve ATP transporters may play an important role in the disposition of chemotherapy in the context of ocular tumor control." (PMID 27467588, 2016). "To further validate ABCB1 as a potential mediator of carboplatin resistance, we treated retinoblastoma cells with carboplatin with or without tariquidar and found that this compound significantly reduced resistance to carboplatin." (PMID 36230889, 2022). "Our results showed that single exposure to chemotherapy or even longer and continuous treatments with melphalan or topotecan at the IC50 did not alter ABCB1, ABCC1, or ABCG2 expression levels in retinoblastoma and HUVEC cells." (PMID 27467588, 2016). "However, ZEB1 (FC = 77.2, p < 0.05), SNAI2 (FC = 3.32, p < 0.05), ABCB1 (FC = 4.4, p < 0.05), and CTSL (FC = −3.8, p < 0.05) expressions were significantly downregulated in non-advanced Rb tumors." (PMID 36291907, 2022).